IGKV3D-20 (immunoglobulin kappa variable 3D-20)
Description:
V region of the variable domain of immunoglobulin light chains that participates in the antigen recognition. Immunoglobulins, also known as antibodies, are membrane-bound or secreted glycoproteins produced by B lymphocytes. In the recognition phase of humoral immunity, the membrane-bound immunoglobulins serve as receptors which, upon binding of a specific antigen, trigger the clonal expansion and differentiation of B lymphocytes into immunoglobulins-secreting plasma cells. Secreted immunoglobulins mediate the effector phase of humoral immunity, which results in the elimination of bound antigens. The antigen binding site is formed by the variable domain of one heavy chain, together with that of its associated light chain. Thus, each immunoglobulin has two antigen binding sites with remarkable affinity for a particular antigen. The variable domains are assembled by a process called V-(D)-J rearrangement and can then be subjected to somatic hypermutations which, after exposure to antigen and selection, allow affinity maturation for a particular antigen.
Synonyms: A11; A11a; IGKV3D20
Gene: Immunoglobulin variable (V) gene on chromosome 2 (90,038,848 to 90,039,479, forward strand). Ensembl gene ENSG00000211625.
Subcellular location: Secreted; Cell membrane
Subcellular location (Human Protein Atlas): Cytosol; Plasma membrane; Predicted to be secreted
Pathways (Reactome):
Immune System: Antigen activates B Cell Receptor (BCR) leading to generation of second messengers; CD22 mediated BCR regulation; Classical antibody-mediated complement activation; FCERI mediated Ca+2 mobilization; FCERI mediated MAPK activation; FCERI mediated NF-kB activation; FCGR activation; Fc epsilon receptor (FCERI) signaling; Immunoregulatory interactions between a Lymphoid and a non-Lymphoid cell; Initial triggering of complement; Regulation of Complement cascade; Regulation of actin dynamics for phagocytic cup formation; Role of LAT2/NTAL/LAB on calcium mobilization; Role of phospholipids in phagocytosis
Disease: FCGR3A-mediated IL10 synthesis; FCGR3A-mediated phagocytosis; Potential therapeutics for SARS
Hemostasis: Cell surface interactions at the vascular wall
Vesicle-mediated transport: Scavenging of heme from plasma
Gene Ontology:
Biological process: immune response
Cellular component: extracellular region; immunoglobulin complex; plasma membrane
Homologues: Orthologues: mouse Igkv18-36 (67% identical), rat Igkvl13 (62% identical). Paralogues in human: IGKV3-20 (97% identical), IGKV3-11 (91% identical), IGKV3D-11 (89% identical), IGKV3OR2-268 (88% identical), IGKV3-15 (85% identical), IGKV3D-15 (85% identical), IGKV3-7 (84% identical), IGKV3D-7 (84% identical), IGKV1D-13 (71% identical), IGKV1-39 (69% identical), IGKV1-5 (69% identical), IGKV1-9 (69% identical), and 81 more.
Diseases named in the same sentence as IGKV3D-20 in open-access papers:
IGKV3D-20 is named in the same sentence as 4 diseases in open-access papers, as found by Europe PMC text mining. Sharing a sentence is not in itself a finding about the gene and the disease.
IGKV3D-20 shares sentences with these, for which no sentence is quoted: colorectal cancer (1 paper); infection (1); tumor (1); virus infection (1).